FMR1 (fragile X messenger ribonucleoprotein 1)
Diseases named in the same sentence as FMR1 in open-access papers (continued):
Sharing a sentence is not in itself a finding about the gene and the disease.
genetic disorder (34 papers, 2011 to 2026). "Fragile X chromosome-associated syndromes are rare genetic diseases caused by dynamic mutations of the fragile X messenger ribonucleoprotein 1 (FMR1) gene located on the X chromosome." (PMID 40377206, 2025). "Fragile X-related disorders (FXDs) are a group of human genetic disorders caused by an increase in the size of a CGG repeat tract in the 5’-untranslated region of the fragile X messenger ribonucleoprotein 1 (FMR1) gene on the X chromosome." (PMID 40141297, 2025). "It is a genetic disorder caused by the loss of the X-linked Fmr1 gene product, named fragile X mental retardation protein (FMRP), a mRNA binding protein involved in translational regulation." (PMID 39767793, 2024). "FXS is a genetic disorder caused by a cytosine-guanine-guanine (CGG) tri-nucleotide expansion in the Fragile X Messenger Ribonucleoprotein gene 1 (FMR1) situated on the bottom end of the X chromosome, leading to the loss of its expressed protein, FMRP." (PMID 39251926, 2024). "Future studies are needed to determine how underlying pathology of FMR1 as well as environmental factors including the stress of having a genetic disorder contribute to cognitive flexibility deficits and psychiatric features in females with FXS." (PMID 36688132, 2022). "FXS is a genetic disorder caused by an unstable expansion of the CGG trinucleotide within the FMR1 gene." (PMID 31354578, 2019). "Fragile X‐associated tremor/ataxia syndrome (FXTAS) is a genetic disorder caused by an expanded CGG trinucleotide repeat located in the 5′ untranslated region of the fragile X mental retardation 1 (FMR1) gene." (PMID 31158927, 2019). "Fragile X syndrome (FXS) is a genetic disorder caused by a mutation of the fragile X mental retardation 1 (FMR1) gene on the X chromosome." (PMID 29719633, 2018). "Fragile X syndrome (FXS) is a genetic disorder caused by an expansion of CGG/CCG tandem repeats in the Fragile X Mental Retardation 1 gene (FMR1) on the X chromosome." (PMID 30227633, 2018). "Fragile X syndrome (FXS) is a genetic disorder caused by the expansion of CGG/CCG tandem repeats in the Fragile X Mental Retardation 1 gene (FMR1) on the X chromosome." (PMID 30227633, 2018).
neurological disorders (27 papers, 2011 to 2025). "SERBP1-associated proteins contain several factors involved in neurological disorders and neurodegenerative diseases, including FMR1, SMN1, and PABPN1." (PMID 39937575, 2025). "Although primarily studied in neurological disorders, recent research indicates that FMR1 also play a role in immune regulation." (PMID 40861493, 2025). "We identified the fragile X messenger ribonucleoprotein 1 (FMRP), an RNA-binding protein implicated in neurological disorders, as a Dynlrb1’s interactor and showed that it undergoes retrograde axonal transport with lysosomes in sensory neurons." (PMID 37739344, 2023). "FXS, which results from the inactivation of the FMR1 gene encoding FMRP, is a representative example of monogenic neurological disorders." (PMID 38003508, 2023). "We used a collection of whole-genome sequencing (WGS) samples described in a recent study of subjects with suspected neurological disorders and additional samples with PCR-validated FMR1 and DMPK repeats from the 100,000 Genomes Project." (PMID 35948990, 2022). "Overall, understanding how epigenetic changes influence neuroanatomy, executive function and clinical outcomes is highly important for both FMR1 PM- and FM-related disorders, and broader neurological disorders influenced by abnormal XCI." (PMID 27959330, 2016). "This also suggests that FMR1 intron 1 methylation in peripheral blood is important when considering XCI in neurological disorders without a PM expansion." (PMID 27959330, 2016).
psychiatric disorder (19 papers, 2013 to 2024). A disorder characterized by behavioral and/or psychological abnormalities, often accompanied by physical symptoms. "One in vitro report indirectly investigated the impact of celastrol on the expression of specific genes, such as Fragile X Mental Retardation 1 (FMR1), linked to different psychiatric diseases, including schizophrenia." (PMID 31694174, 2019). "Furthermore, carriers of premutated FMR1 alleles (reduced FMRP levels) have been associated with a significant degree of psychiatric disorders." (PMID 24167470, 2013). "A similar compensatory mechanism is found in other models of psychiatric disorders such as Fmr1-/y mice where changes in intrinsic neuronal excitability dominate the resulting perturbations in network processing including dendritic integration and synaptic plasticity." (PMID 35115661, 2022). "In GenRED sib-pair DNA, the estimated number of FMR1 5′ UTR trinucleotide repeats averaged 24 in affected sibs and 24 in sibs without mental illness." (PMID 23521777, 2013).
neurodegenerative disease (13 papers, 2015 to 2025). A disorder of the central nervous system characterized by gradual and progressive loss of neural tissue and neurologic function. "Fragile X-related tremor/ataxia syndrome (FXTAS) is another member of the polyG neurodegenerative disease family, caused by GGC repeat expansion in 5’-UTR of FMR1." (PMID 39609868, 2024). "Diagnosing a FMR1-premutation carrier remains challenging, as the clinical features overlap with other neurodegenerative diseases." (PMID 33709078, 2021). "Contradictory results obtained from morphants and mutants regarding SpMN axon outgrowth phenotypes have been described previously for other genes related to neurodegenerative diseases, e.g. Tardbp and Fragile X mental retardation 1 (Fmr1)." (PMID 25785851, 2015). "Consequently, diagnosing a FMR1-premutation carrier remains challenging, as the clinical features may overlap with other neurodegenerative diseases." (PMID 33709078, 2021).
movement disorder (8 papers, 2011 to 2024). Neurological conditions resulting in abnormal voluntary or involuntary movement, which may impact the speed, fluency, quality and ease of movement. "We included a cohort of 2,362 PD patients and 1,072 controls from the Parkinson’s Disease and Movement Disorders Multicenter Database and Collaborative Network in China (PD-MDCNC) in this study and conducted repeat-primed polymerase chain reaction (RP-PCR) for the size of FMR1 CGG repeat expansions." (PMID 37583466, 2023).
infection (6 papers, 2020 to 2025). The state of being infected such as from the introduction of a foreign agent such as serum, vaccine, antigenic substance or organism. "This study explored the interaction between the FMR1 gene and a viral-like infection as an environmental insult, focusing on the impact on core autistic-like behaviors and the mGluR1/5-mTOR pathway." (PMID 39604505, 2025). "It remains to be determined if persons with FXS are more susceptible to infection by SARS-CoV-2 and other viruses, and conversely, if the FMR1 premutation is protective against viral infection." (PMID 32984339, 2020).
brain disorder (2 papers, 2018 to 2021). A disease affecting the brain or part of the brain. "The network revealed that the majority of the disorders are linked with DYNC1H1 (k = 91), LMNA (k = 86), FMR1 (k = 74), DCTN1 (k = 57), and ALDH18A1 (k = 54) genes and showed interactions with multiple brain disorders." (PMID 34832615, 2021).
connective tissue disorder (2 papers, 2020 to 2022). A disease involving the connective tissue. "In those females with normal NGS testing for connective tissue disorders, the FMR1 gene was then analyzed using CGG repeat expansion studies." (PMID 36012355, 2022). "Recently, FMR1 premutation repeat expansion or carrier status has been reported in individuals with connective tissue disorder-related symptoms." (PMID 36012355, 2022).
FMR1 also shares sentences with these, for which no sentence is quoted: Down syndrome (7 papers); hepatocellular carcinoma (6); cerebellar ataxia (5); cognitive decline (5); Prader-Willi syndrome (5); spinal muscular atrophy (5); essential tremor (4); Kennedy disease (4); hypogonadism (3); Macroorchidism (3); neurofibromatosis (3); Phelan-McDermid syndrome (3); scoliosis (3); 22q11.2 deletion syndrome (2); acral lentiginous melanoma (2); Action tremor (2); Adult onset (2); autonomic dysfunction (2); breast tumor (2); cognitive disorder (2); Duchenne muscular dystrophy (2); hereditary ataxia (2); Huntington disease-like 2 (2); intellectual disability syndrome (2); language disorder (2); metabolic disease (2); multiple sclerosis (2); Myotonic dystrophies (2); neuropathy (2); psychosis (2).
A further 122 diseases each share a sentence with FMR1 in 2 papers or fewer.